MIR122HG (MIR122 host gene)
Synonyms: lnc-pri-miR-122
Gene: Long non-coding RNA gene on chromosome 18 (58,445,788 to 58,453,766, forward strand). Ensembl gene ENSG00000267391.
Gene Ontology:
Biological process: miRNA-mediated post-transcriptional gene silencing
Cellular component: RISC complex